OR9A4 (olfactory receptor family 9 subfamily A member 4)
Description:
Odorant receptor.
Tractability: Antibody: UniProt places it where antibodies can reach, with medium confidence; UniProt predicts a signal peptide or a membrane-spanning region; its Gene Ontology location is reachable by antibodies, with medium confidence.
Gene: Protein-coding gene on chromosome 7 (141,916,399 to 141,920,625, forward strand). Ensembl gene ENSG00000258083.
Subcellular location: Cell membrane
Pathways (Reactome):
Sensory Perception: Expression and translocation of olfactory receptors
Gene Ontology:
Molecular function: G protein-coupled receptor activity; olfactory receptor activity
Biological process: detection of chemical stimulus involved in sensory perception of smell; G protein-coupled receptor signaling pathway
Cellular component: membrane; plasma membrane
Genetic constraint (gnomAD): Loss-of-function variants: 16 observed, 17.85 expected, observed/expected ratio (o/e) 0.9, 90% interval 0.61 to 1.36. The upper end of that interval is the gene's LOEUF score, 1.36, which puts it in group 5 of 6, group 1 being the genes least tolerant of losing a copy. Missense variants: 391 observed, 401.66 expected, observed/expected ratio (o/e) 0.97, 90% interval 0.89 to 1.06. Synonymous variants: 167 observed, 151.26 expected, observed/expected ratio (o/e) 1.1, 90% interval 0.97 to 1.25.
Homologues: Orthologues: dog OR9A4 (89% identical), dog OR9A4C (85% identical), mouse Or9a4 (84% identical), rat Or9a4 (83% identical), macaque OR9A4 (81% identical). Paralogues in human: OR9A2 (76% identical), OR9A1P (73% identical), OR11G2 (40% identical), OR11H4 (37% identical), OR11H6 (37% identical), OR10X1 (37% identical), OR11H7 (36% identical), OR11A1 (35% identical), OR11H12 (35% identical), OR11H1 (34% identical), OR11H2 (34% identical), OR9G1 (34% identical), and 21 more.
Diseases named in the same sentence as OR9A4 in open-access papers:
OR9A4 is named in the same sentence as 1 disease in open-access papers, as found by Europe PMC text mining. Sharing a sentence is not in itself a finding about the gene and the disease. The quoted sentences say what the papers report.
Sleep apnea (1 paper, 2023). An intermittent cessation of airflow at the mouth and nose during sleep is known as sleep apnea. "The results showed that Lasso regression identified a total of seven genes as the characteristic genes of sleep apnea, which are: C12orf54, FOS, GPR1, OR9A4, MYO5B, RAB39B, KLHL4, as the core genes of follow-up research and construction of prediction models." (PMID 38077447, 2023). "The expression levels of hub genes and sleep apnea-related genes were significantly correlated, among which KILH4 and BCHE were significantly positively correlated (Pearson r = 0.897), OR9A4 Significantly negative correlation with ADIPOQ (Pearson r = −0.762)." (PMID 38077447, 2023).